OR56B4 (olfactory receptor family 56 subfamily B member 4)
Description:
Odorant receptor.
Synonyms: OR11-67
Tractability: Antibody: UniProt places it where antibodies can reach, with medium confidence; UniProt predicts a signal peptide or a membrane-spanning region; its Gene Ontology location is reachable by antibodies, with medium confidence.
Gene: Protein-coding gene on chromosome 11 (6,107,684 to 6,108,835, forward strand). Ensembl gene ENSG00000180919.
Subcellular location: Cell membrane
Pathways (Reactome):
Sensory Perception: Expression and translocation of olfactory receptors
Gene Ontology:
Molecular function: olfactory receptor activity; signaling receptor activity
Biological process: cellular response to lipid; detection of chemical stimulus involved in sensory perception of smell; G protein-coupled receptor signaling pathway; system process
Cellular component: plasma membrane; membrane
Genetic constraint (gnomAD): Loss-of-function variants: 1 observed, 0.51 expected, observed/expected ratio (o/e) 1.95. That is too few expected variants to judge how well the gene tolerates losing a copy. Missense variants: 447 observed, 403.29 expected, observed/expected ratio (o/e) 1.11, 90% interval 1.02 to 1.2. Synonymous variants: 142 observed, 155.99 expected, observed/expected ratio (o/e) 0.91, 90% interval 0.79 to 1.05.
Homologues: Orthologues: chimpanzee OR56B4 (98% identical), rabbit OR56B4 (73% identical), guinea pig OR56B4 (73% identical), dog OR56B6 (72% identical), mouse Or56b34 (71% identical), mouse Or56b35 (70% identical), rat Or56b6 (69% identical), rat Or56b6c (69% identical), tropical clawed frog or56c1 (40% identical). Paralogues in human: OR56B1 (65% identical), OR56B2 (65% identical), OR52L1 (39% identical), OR52D1 (38% identical), OR52B2 (38% identical), OR52E6 (38% identical), OR52E8 (38% identical), OR52B4 (38% identical), OR52B6 (37% identical), OR52K2 (37% identical), OR51E1 (37% identical), OR52K1 (37% identical), and 39 more.